IGF1R (insulin like growth factor 1 receptor)
Diseases named in the same sentence as IGF1R in open-access papers (continued):
Sharing a sentence is not in itself a finding about the gene and the disease.
cancer (continued). "Hence, the mTORC1/HIF1α/IGFBP5 axis may play a general role in restricting IGF1R-driven PI3K/AKT activity in (breast) cancer cells." (PMID 36093095, 2022). "However, IGF-1R is generally overexpressed in cancers and can be detected in most solid tumors." (PMID 34359752, 2021). "The involvement of the IGF-1R pathway and the potential role of miRNAs in cancer therapy prompted us to seek out dysregulating miRNAs that could be involved in the insulin/IGF-1R signaling pathway, as these miRNAs may represent potential PDAC therapeutic targets." (PMID 34440625, 2021). "Insulin-like growth factor 1 receptor (IGF1R) gene expressed by cancer cells was highly associated with estrogen response signatures in BC, which may demonstrate that the binding effect of IGF1 on IGF1R as well as activating estrogen signaling enhanced cancer growth." (PMID 34676217, 2021). "Besides, promoter methylation of IGF-1R, IGF-1, IGF-II, and especially IGFBP-3 in various regions could be associated with cancer prognosis." (PMID 33768092, 2021). "Moreover, the PKM2/IGF-1R signaling-mediated increase in glycolysis may contribute to the adaptive response of cancer cells to hypoxia." (PMID 34359752, 2021). "Since cancer is a leading cause of death worldwide, and the low efficacy of many existing therapies is a major clinical challenge, it is essential to understand the prognostic and immunological impact of IGF-1 and IGF-1R among cancer types comprehensively in order to develop novel immunotherapies." (PMID 34804946, 2021). "Interestingly, a crosstalk between CXCR4 and IGF1R in cancer cells has been described." (PMID 33673232, 2021). "Proteoglycans are mainly produced by the cancer-associated fibroblasts (CAFs) in the stroma and play a role in intercellular and ECM interactions via activation of receptor tyrosine kinases (EGFR, FGFR, IGF1R, INSR) on the cancer cells regulating the proliferation and survival cascaded." (PMID 34851463, 2021). "IGF-2 also binds to IGF-1R and may lead to cancer cell proliferation in HCC patients." (PMID 33669204, 2021). "Moreover, overexpression of PSPC1 or other paraspeckle proteins may be a potential biomarker for identification of subgroups of cancer patients for treatment with IGF1R inhibitor." (PMID 32570949, 2020). "The receptor of IGF‐1 (IGF‐1R) with the combination of IGF‐1 could exert vital function in cancer such as regulating cancer stem cell, epithelial‐mesenchymal transition and tumour microenvironment, which further influence cancer progression, metastasis and angiogenesis." (PMID 32548873, 2020). "Finally, we investigated the function of the IGF1R/PCNA interaction in several cancer cell lines." (PMID 32701997, 2020). "However, it is becoming ever more clear that IGF-1R endocytosis and trafficking to specific subcellular locations can define specific signaling responses that are important for key biological processes in normal cells and cancer cells." (PMID 33584548, 2020). "This indicates that IGF-1R may promote the transcriptional expression of EWS fusion genes by inducing distinct cellular pathways involved in the pathogenesis of various types of cancer." (PMID 32754598, 2020). "Our recent discovery that IGF1R could increase cellular tolerance to DNA replication stress by direct phosphorylation of PCNA in stem cells prompted us to investigate this mechanism in cancer cells." (PMID 32701997, 2020). "However, few studies have reported the relationship between abnormal IGF1R and cancers." (PMID 32665850, 2020). "IGF1R, one of the members of the insulin/IGF system, was mostly expressed in foetal and cancer tissues 39 and three CpG islands are predicted in the promoter region of IGF1R which may combine large list of transcript factors including MZF1, TCFL5, USF1, ETS1 and SPIB." (PMID 33085184, 2020). "Golgi-derived IGF-1R signaling might therefore contribute to aggressive cancer cell behavior." (PMID 33584548, 2020).
cancer (continued). "Furthermore, IGF-1R is a target in cancer biology as it is important for cell growth." (PMID 33320095, 2020). "A better knowledge may have important implications, considering that in clinical trials the target therapy with inhibition of IGF-1R is often inadequate to inhibit cancer progression, probably because the mitogenic signal might be propagated by the IR, an alternative pathway to the inhibited IGF-1R." (PMID 30453495, 2018). "Thus, suppressing IGF-1R might be an effective therapeutic strategy to attenuate the proliferation of cancer cells, especially for the cancer cells which have higher expressions of IGF-1R." (PMID 30213025, 2018). "Also in this group, IGF1R phosphorylation was increased in cancer tissue." (PMID 29662006, 2018). "Moreover, IR-A content in HR ER+ cancers was higher than IGF-1R content." (PMID 30453495, 2018). "However, IGF-1R inhibitors have shown limited benefit in cancer when used as single therapy." (PMID 28591735, 2017). "However, although other evidence supports that the inhibition of N-glycan biosynthesis enhances the effects of radiation in cancer cells, it remains unclear how changes in INSR/IGF1R-linked N-glycans could interfere with radiosensitivity in cancer cells." (PMID 28880250, 2017). "Therefore, ALK and IGF-1R are independent drug targets according to the criterion developed by Bozic and Nowak19,20 in their models of drug combination to overcome cancer resistance, and our results are consistent with their proposal that combination therapy will be more effective than monotherapy." (PMID 29066738, 2017). "IGF1R activation could also promote EMT in some types of cancer cells." (PMID 29190911, 2017). "Therefore, the IGF1R is a potential cancer treatment target." (PMID 29212217, 2017). "Thus, IRA through dimerization with IGF-1R (IGF-1R:IR) or homo-dimerization may provide mitogenic stimuli to cancer cells via IGF-2 activation." (PMID 27765027, 2016). "Hence, IGF-1R has been proposed as a promising target for cancer therapeutics." (PMID 27813495, 2016). "Additionally, hybrid receptors of IR and IGF-1R have been found in different cancer cells and may also play a prominent role in carcinogenesis." (PMID 27849005, 2016). "Thus, specific small-molecule inhibitors of PKC-θ could be developed for combination therapy with EP2/EP4 antagonists to exploit this novel molecular target for cancers that co-express IGF-1R, EP2 or EP4, and PKC-θ." (PMID 25638159, 2015). "Determining the key regulators of IGF-1R expression and how their expression is regulated in phenotypically distinct cancers may unlock new ways to target invasiveness and resistance to kinase inhibitors and conventional cancer therapies." (PMID 26191041, 2015). "Therefore, effective regimens to inactivate the IGF-1R pathway may sensitize cancer cells to anticancer therapies and provide clinical benefits to cancer patients." (PMID 26041671, 2015). "Therefore, it could be established that the IGF-1R blockade appeared to increase cancer metastasis in animal models of three different types of human cancers." (PMID 26465273, 2015). "Once cancer has been established, the importance of IGF-1R for disease progression remains unclear." (PMID 25743390, 2015). "Therefore, successful targeting IGF1R has a broad impact on cancer treatment." (PMID 26173023, 2015). "Although the resistance mechanism of IGF-1R inhibitors remains largely unclear, candidate drugs, including monoclonal antibodies, small molecule tyrosine kinase inhibitors and ligand binding antibodies, are being introduced in phase I and II studies for a wide variety of cancers." (PMID 24765137, 2014). "Thus, IGF1R over-expression is a typical feature of most pediatric cancers and other solid tumors (e.g., brain and kidney), whereas the situation with adult epithelial tumors (e.g., breast and prostate) is more complex and reduced IGF1R levels are often seen in advanced stage diseases." (PMID 24904527, 2014).
cancer (continued). "Therefore, the modulation of IGF1R by miR-143/145 may explain why the downregulation of miR-143/145 during colorectal carcinogenesis can promote cancer progression." (PMID 25474488, 2014). "However, upregulation of growth factors and their receptors, like IGF1R, may contribute to crossing the final hurdle towards cancer development." (PMID 24813441, 2014). "Indeed, IGF1R is overexpressed in several primary tumors and cancer-derived cells." (PMID 25110710, 2014). "While no recurrent cancer-specific mutations of the IGF-1R or its ligands have been described to date, a plethora of studies have provided evidence for a link between this signaling pathway and the risk of developing cancer." (PMID 23525758, 2013). "Identification of specific mechanistic functions of IGF1R/PKA signaling could have potential for impact upon the development of therapeutic strategies for IGF1R-dependent cancer by shifting the balance of these 2 pathways away from cell survival towards cell death." (PMID 24083380, 2013). "Similarly, IGF1R inhibition in combination with EGFR inhibition in EGFR over-expressing cancer cells or IGF1R inhibition in combination with HER2 inhibition in HER2 positive cancer cells have also shown improved results over the use of single agents only." (PMID 24244833, 2013). "Moreover, insulin receptor (IR), closely related to IGF-1R, is also overexpressed in many cancers." (PMID 23696913, 2013). "In addition, while nuclear localization of IGF-1R was recently reported in cancer cells and human corneal epithelial cells, the function and profile of nuclear IGF-1R is unknown." (PMID 22879999, 2012). "To date, no activating IGF1R mutations have been identified in cancers." (PMID 22778948, 2012). "Various chronic glomerulopathy prone conditions such as poorly controlled diabetes, malignant tumors, systemic autoimmune diseases, pregnancy are inclinable to be accompanied endocrinological/metabolic disturbance which may affect expression of InsR or IGF-1R." (PMID 23061721, 2012). "It is noted that the in vitro sensitivity of a certain cancer cell line to growth inhibition by an anti-IGF-1R mAb has been proposed to require a minimal level of IGF-1R expression as well as a functional IGF signaling axis, both of which may contribute to ligand-stimulated proliferation." (PMID 22952934, 2012). "For the second replicated GS-eQTL between the “Pathways in Cancer” GS and the “Neuroactive ligand-receptor interaction” GS, the most significant eQTL association involved SNP rs1160198 from gene GLRA2 and expression of IGF1R (Bonferroni adjusted p-value of 7.95×10−8)." (PMID 22905253, 2012). "Similarly, in cancer cells, recent reports indicate that nuclear IGF-1R may function to regulate gene expression as a transcriptional modulator." (PMID 22879999, 2012). "Overexpression of IGF-1R can promote the growth of breast carcinoma cells, and it might be related to induction of tumor apoptosis and stimulation of an immune reaction to remove residual carcinoma cells." (PMID 22217202, 2012). "Therefore, IGF-1R directed therapy likely offers little if any benefit for this cancer type." (PMID 24212944, 2011). "However, we can speculate that insulin may modulate cancer development through both the insulin receptor and insulin like growth factor-1 receptor (IGF-1R)." (PMID 20436918, 2010). "In murine cancer models methylation changes in the differentially methylated region 2 of IGF2 have been associated with overexpression of IGF2, which in turn might activate IGF1R signalling and increase cell growth." (PMID 20338046, 2010). "Furthermore, IGF-1R mutant cancers may benefit from targeted inhibition of the MMEJ pathway." (PMID 42095258, 2026). "Inhibition of IGF1R in this context reduces residual disease burden and cancer recurrence, underscoring the broader relevance of IGF1 signaling in KRAS driven cancer." (PMID 41526435, 2026).
cancer (continued). "As we mentioned in the previous treatment section, Tel has been confirmed to down-regulate the expression of FOXA1 through the IGF1-R/AKT/FOXA1 pathway, to inhibit the proliferation of cancer cells in ER-positive breast cancer." (PMID 40003882, 2025). "Signaling through insulin like growth factor 1 receptor (IGF1R) and insulin receptor (IR) promotes cancer cell proliferation, survival, and treatment resistance in diverse malignancies." (PMID 39919036, 2025). "Its levels were found to be significantly reduced in cancer cells, and in silico analysis revealed that the 3′-UTR of IGF-1R was among the predicted putative targets of the IGF-1 pathway." (PMID 41153350, 2025). "Triple combination therapy with oHSV, RTx, and IGF1R blockade synergistically improved survival, abolished YAP1 expression, and reduced cancer cell self-renewal." (PMID 41510300, 2025). "IGF-1R, the receptor of IGF-2, is recognized as a promising target of cancer therapy, and monoclonal antibodies targeting human IGF-1R have been studied in clinical trials." (PMID 40394007, 2025). "IGF‐1 then binds to its IGF‐1R, activating key oncogenic pathways such as PI3K/AKT/mTOR and MAPK/ERK, which drive cell proliferation, survival, and metabolic adaptation in cancer cells." (PMID 40387523, 2025). "Their work allowed cancer cell isolation/enrichment, optical imaging, multiplex SERS detection for four cancer biomarkers (EpCAM, HER2, CD44, and IGF1R), as well as molecular profiling of various breast cancer cell lines." (PMID 39997827, 2025). "Type 1 IGF receptor (IGF-1R) is a key IGF axis component and is considered to be an oncogene in several cancer cell lines." (PMID 40282476, 2025). "We discovered and validated that concurrent targeting of FYN, along with other tyrosine kinases such as IGF1R, EGFR, or ABL2 can synergistically eradicate TNBC and impede cancer growth." (PMID 40243589, 2025). "PHB2 in the plasma membrane directly contacts insulin-like growth factor binding protein 6 (IGFBP 6) and regulates cancer cell migration by activating MAP kinases, IGF1R (GALNT14/PHB2/IGF1R)." (PMID 38813101, 2024). "IGF1R attenuation is achievable by IGF1R inhibitors, and IGF1 is deemed a provocative target in anti-cancer research, supported by a plethora of studies." (PMID 39000545, 2024). "The IGF-1R CT, which contains Tyr1250/1251, distinguishes IGF-1R and IR signaling, and enhances IGF-1R signaling that supports cellular transformation and aggressive cancer phenotypes." (PMID 39608716, 2024). "The IGF-1R is activated by binding to the growth factors IGF-1 and IGF-2 and overexpressed in various cancers." (PMID 38835346, 2024). "The direct modulation of the PI3K/Akt and insulin-like growth factor-1 receptor (IGF-1R) pathways have also been examined, both of which play key roles in cancer cell proliferation." (PMID 38398503, 2024). "IGF is produced by osteoblasts and acts through its receptor IGF1R to activate downstream protein kinases, including those in the MAPK/ERK 1/2 signaling pathway that regulate cancer cell growth and survival." (PMID 38347067, 2024). "The integrin/ILK/NF-κB, IGF1R/PI3K/AKT, and Wnt/β-catenin pathways, as well as certain micro-RNAs have been proven to regulate or be regulated by IGFBP2 in a variety of malignant tumors." (PMID 39221034, 2024). "Several monoclonal antibodies targeting IGF1R or IGF1 proteins have been tested in the clinic for different diseases, including cancer." (PMID 38420122, 2024). "IGF-1R and IR activate an intracellular signal primarily through the phosphatidylinositol 3-kinase-AKT (PI3K-AKT) pathway in human cancers leading to mitogenesis, invasion, and apoptosis protection." (PMID 39335147, 2024). "The axis represented by IGF1 and its receptor, the insulin-like growth factor 1 receptor (IGF1R), is deregulated in many cancer cell types." (PMID 38420122, 2024).
cancer (continued). "The top 10 cancer-related pathways included EGFR (ERBB1) downstream signaling, FGF signaling pathway, IGF1R signaling cascade, IRS-mediated signaling, and PI3K cascade." (PMID 38542291, 2024). "Downregulation of KLOTHO by different epigenetic mechanisms has been reported in several types of cancer, resulting in aberrations in FGF signaling, as well as disturbed insulin-like growth factor 1 receptor (IGF-1R) and the Wnt/β-catenin signaling pathway." (PMID 39199335, 2024). "In the autocrine/paracrine signaling loops of cancer cells, in particular, IGF2 working through IGF-1R and/or IR-A is frequently observed." (PMID 38542291, 2024). "In cancer, since IGF-1 is a potent cytoprotective signal, IGF-1/IGF-1R activity has been long ago established as pro-tumorigenic." (PMID 39638246, 2024). "In migratory cancer cells, which express high levels of ITGB1, suppression of ITGB1 increased IGF-1R stability and its retention on the plasma membrane during cell adhesion." (PMID 39608716, 2024). "Pathway analysis revealed enrichment in cancer-related pathways, notably EGFR downstream signaling and IGF1R signaling." (PMID 38542291, 2024). "At the same time, we also found positively selected differentially edited sites in a series of cancer immune genes, including EGF, IGF1R, and PIK3CD." (PMID 36895481, 2023). "eHSP90 has been observed to interact with several receptors and signaling pathways involved in cancer, including the EGFR, vascular endothelial growth factor receptor (VEGFR), and IGF-1R." (PMID 36902446, 2023). "Results revealed a significant up-regulation of MCL1 and CCND1, and a significant down-regulation of IGF1R and PTEN in KIRC patients with varying cancer stages, races, genders, and age groups compared to normal controls." (PMID 37744271, 2023). "Activated IGF-1R can also stabilize integrins and promote epithelial–mesenchymal transition (EMT), thereby facilitating cancer metastasis." (PMID 37834454, 2023). "The role of IGF‐1R, IGF‐1, and IGF‐2 signaling in the development, maintenance, and progression of cancers is well established." (PMID 37042307, 2023). "Cells positive for NRP1 (NRP1med and NRP1hi cells) or IGF1R (IGF1Rmed and IGF1Rhi cells) and cells positive for FXYD3 (FXYD3med and FXYD3hi cells) were more abundant among P3 patient-derived cancer cells than in P6 and P1 patient-derived cells, respectively." (PMID 37966117, 2023). "These mutations represent additional insight into how genes such as IGF1R, MSI2, MBD2, and ASCL1 can be aberrantly regulated in cancer, highlighting the importance of expanding the field’s view of cancer genomics to include alterations in UTRs." (PMID 37516102, 2023). "IGF-1R inhibition or ablation inhibited FVIIa-mediated activation of AKT and prevented the protection of cancer cells from TRAIL-induced apoptosis." (PMID 36900315, 2023). "Radiotherapy to CAFs induced insulin-like growth factor-1 (IGF1) and stimulated survival of cancer cells, which was restrained by IGF1 receptor (IGF1R) neutralization." (PMID 37784036, 2023). "Our results suggest potentially critical roles of hydroxymethylation of CpGs located within the gene body regions in regulating the gene expression of critical cancer genes, like HDAC4 and IGF1R." (PMID 36909536, 2023). "The ability of TF/FVIIa to protect cancer cells from TRAIL-induced apoptosis and stimulate IGF-1R-dependent protein synthesis was eliminated by inhibiting ITGβ1 or Src, or by Cav1 activation." (PMID 36900315, 2023). "These miR-99 family members negatively regulate IGF1R or downstream protein synthesis signaling molecules, including MTOR and RPTOR in cancer cells, macrophages, and dermal cells." (PMID 35159261, 2022). "BMS-536924, an ATP-competitive IGF1R inhibitor, can suppress the IGF1R-induced phosphorylation of phosphoinositide 3-kinase (PI3K)/ protein kinase B (AKT), consequently repressing cancer cell proliferation and differentiation." (PMID 35668527, 2022).